IGF1R (insulin like growth factor 1 receptor)
Diseases named in the same sentence as IGF1R in open-access papers (continued):
Sharing a sentence is not in itself a finding about the gene and the disease.
pulmonary hypertension (7 papers, 2018 to 2025). Increased pressure within the pulmonary circulation due to lung or heart disorder. "In the myocardium and pulmonary aorta of rats with pulmonary arterial hypertension, the expression of miR-200a-3p is upregulated, inhibiting the expression of IGF1R and PDCD4." (PMID 40997050, 2025). "Additionally, knockdown of IGF1R or IGF-1 activity has previously been shown to ameliorate the effects of chronic hypoxia-induced pulmonary hypertension." (PMID 41132156, 2025). "Decreased expression of miR-223 results in the upregulation of IGF-1R and enhances IGF-1/IGF-1R signaling that mediates right ventricular hypertrophy in the pathophysiology of pulmonary hypertension." (PMID 33511137, 2020). "In conclusion, circDiaph3 plays an important role in promoting the proliferation of pulmonary artery smooth muscle cells in rats with pulmonary hypertension through IGF1R and PI3K/AKT/mTOR signaling pathways, suggesting the potential value of circDiaph3 in the treatment of pulmonary hypertension." (PMID 37705862, 2023).
thymic carcinoma (7 papers, 2015 to 2023). Thymic carcinoma (TC) is a type of thymic epithelial neoplasm characterized by a high malignant potential. "IGF-1R is highly expressed in thymic carcinomas (92%), and occasional mutations of IGF1R, including G596V, have been reported." (PMID 38201593, 2023). "In this study, frequently mutated genes in thymic carcinomas included KIT, DDR2, PDGFRA, ROS1, and IGF1R." (PMID 35884448, 2022). "Bcl-2, calretinin, CD5, CD117, CEA, GLUT1, IGF-1R, mesothelin, MOC31, MUC1, and p21 were higher expressed in thymic carcinomas." (PMID 35565429, 2022).
uveal melanoma (7 papers, 2016 to 2024). A melanoma derived from melanocytes of the uveal tract. "Moreover, high levels of IGF-1R expression are associated with poorer survival in patients with uveal melanoma." (PMID 27764776, 2016). "IGF-1R expression has been shown to significantly correlate with worse prognosis in uveal melanoma patients." (PMID 32976223, 2020). "Moreover, we investigated the combination of targeted inhibitors of DNA-PKcs and IGF1R with everolimus on uveal melanoma in an in vivo model." (PMID 35804957, 2022). "Thus, targeting IGF-1R with IMC-A12 may have the potential to control metastasis in uveal melanoma patients." (PMID 32976223, 2020). "We verified these hits effects genetically: we treated the uveal melanoma cell lines depleted of PRKDC or IGF1R with everolimus and, in case of IGF1R, observed a synergistic effect." (PMID 35804957, 2022). "Potentially, other liver metastasis interaction for uveal melanoma could be achieved through the c-MET Tyrosine kinase receptor (MET Proto-Oncogene) and Insulin-Like Growth Factor 1 Receptor (IGF-1R)." (PMID 38732371, 2024).
acne (6 papers, 2022 to 2025). An inflammatory process of the sebaceous glands which is characterized by comedones, nodules, papules and/or pustules on the skin. "A previous study has proven that the proliferation of keratinocytes was enhanced by IGF-1 via the activation of IGF-1r in the development of acne vulgaris." (PMID 38197658, 2024). "Among them, IGF-1, IGF-1R and downstream mechanistic target of rapamycin (mTOR) play key roles in the development of acne and the formation of acne-induced PSs." (PMID 38585341, 2024). "Together, our data indicate that BV and melittin suppressed sebum through inhibition of the IGF-1R/PI3K/Akt/SREBP-1 signaling pathway in SZ95 sebocytes offering therapeutic strategies to target lipogenesis in acne." (PMID 35328573, 2022). "IGF-1R was highly expressed in acne-induced PS tissues, and it supports scarring by increasing fibroblast invasiveness and inhibiting their apoptosis; therefore, previous studies suggested that targeting IGF-1R in fibroblasts may help prevent scar formation." (PMID 38585341, 2024). "Some target genes were likely involved in acne development, including AR, IGF1/IGF1R, mTOR, GATA6, Wnt, IL6, FOXO1, PIK3, MYC." (PMID 40625748, 2025). "Among others, IGF-1 and IGF-1R are well-known targets of C. acnes, where IGF-1 induces lipid synthesis in human sebocytes and plays an important role in the development of acne." (PMID 36551286, 2022). "Hence, our findings suggest that BV and melittin inactivate IGF-1R/Akt/mTOR/SREBP and this is likely to be important in the anti-lipogenic action against C. acnes or IGF-1, offering therapeutic strategies to target lipogenesis in acne." (PMID 35328573, 2022).
acromegaly (6 papers, 2014 to 2025). Acromegaly is an acquired disorder related to excessive production of growth hormone (GH) and characterized by progressive somatic disfigurement (mainly involving the face and extremities) and systemic manifestations. "For example, pegvisomant, a growth hormone receptor antagonist, is used for normalizing IGF-1 levels in acromegaly and teprotumumab, which antagonizes IGF-1R, is used to treat thyroid eye disease." (PMID 32492897, 2020). "Meanwhile, Clotho, a potent inhibitor of both IR and IGF-1R via interruption of their tyrosine phosphorylation, has been recently found to be increased in acromegaly, thus, it may also contribute to IGF-1 resistance." (PMID 36882643, 2023). "It suppresses not only ligand-stimulated autophosphorylation of the IGF1R but also activation of signaling events downstream of the IGF1R, which in turn may reduce the activation of the IGF1R in patients with active acromegaly." (PMID 24692508, 2014). "Furthermore, acromegaly may induce IGF-1 resistance due to IGF-1R downregulation or desensitization in the setting of chronic exposure to IGF-1 and concomitant hyperinsulinemia." (PMID 36882643, 2023). "Soluble Klotho (S-Klotho) level is elevated in active acromegaly and it has been suggested that S-Klotho can inhibit activation of the IGF1 receptor (IGF1R)." (PMID 24692508, 2014).
adrenal carcinoma (6 papers, 2008 to 2019). A carcinoma involving a adrenal gland. "Metformin interferes with the proliferative autocrine loop of IGF2/IGF-1R, which supports adrenal cancer growth." (PMID 27391065, 2016). "In vitro studies on adrenal carcinoma cell lines with increased IGF2 expression showed that blocking IGF1R activity resulted in both decreased proliferation and induction of apoptosis, indicating that IGF2 was involved in the control of both processes." (PMID 22952916, 2012). "In order to investigate any involvement of the IGF-1R/ERK axis, which sustains the proliferative autocrine loop in adrenal cancer, we performed western blot analysis on lysates of H295R cells cultured alone or with ASCs for 7 days." (PMID 31817072, 2019).
Anxiety (6 papers, 2015 to 2025). Intense feelings of nervousness, tension, or panic often arise in response to interpersonal stresses. "In particular, suppression of IGF1R signaling in neurons has been shown to protect against neuroinflammation, anxiety, and memory impairments caused by Aβ oligomers." (PMID 39737748, 2025). "As for the hormone encoders, CCK is involved in several activities such as satiety regulation, enzyme secretion, gut motility, and anxiety, whereas IGF1R is an important regulator of intestinal cell growth and differentiation." (PMID 34873196, 2021). "On the other hand, hyperkinesis in dark phase and anxiety, clearly reported for both models, could be connected with deregulated various clock‐controlled metabolic genes involved in insulin signaling and mitochondrial function, for example, Igf1r and Slc2a1." (PMID 39604147, 2024).
bladder tumors (6 papers, 2014 to 2024). "A previous report demonstrated that IGF1R showed more levels and activation in non‐muscle‐invasive bladder tumours than in muscle‐invasive ones." (PMID 38886900, 2024). "Both invasive and superficial (Ta–T1) bladder tumors had higher expression levels of IGF1R compared with normal bladder tissue." (PMID 32795296, 2020). "Concerning IGF1R expression, our results being contradictory with previously published ones, we first studied levels of expression of IGF1R mRNA in others publicly available data for bladder tumors and we then sought to validate them at the protein level." (PMID 28882129, 2017). "We evaluated the activation status of the IGF pathway in bladder tumors, by assessing IGF1R phosphorylation and evaluating its correlation with mRNA levels for IGF pathway components." (PMID 28882129, 2017). "IGF1R expression and activation were stronger in non-muscle-invasive than in muscle-invasive bladder tumors." (PMID 28882129, 2017).
bone cancer (6 papers, 2022 to 2023). A primary or metastatic malignant neoplasm affecting the bone or articular cartilage. "The malignant bone tumors (0.1999) expressed a significant gene level of IGF-1R compared to benign tumors (0.03356) (P < 0.0001)." (PMID 36713521, 2022).
dementia (6 papers, 2019 to 2025). Loss of intellectual abilities interfering with an individual's social and occupational functions. "IGF-1 (insulin-like growth factor-1) is implicated in the etiology of dementia, protects neurons by lowering their sensitivity to oxidative stress, and is strongly correlated with the A allele of the IGF1R polymorphism for VAD." (PMID 38384571, 2024). "Lastly, IGF1R stimulating activity, as noted in 1014 participants in the Rotterdam study, was associated with dementia." (PMID 36771351, 2023). "Deletion of the IGF-1 receptor gene (Igf1r) resulted in an almost complete loss of the DG in mice and impaired learning and memory function, leading to dementia, while exogenous IGF-1 enhanced hippocampal neuronal precursor cells proliferation and directed the generation of mature granule cells." (PMID 40283962, 2025). "IGF-1R mediates its action via IGF-1, and its depletion is incorporated in the pathogenesis of dementia." (PMID 32802484, 2020).
kidney cancer (6 papers, 2012 to 2025). Primary or metastatic malignant neoplasm involving the kidney. "IGF1R was found to be indirectly associated with kidney cancer tumor growth." (PMID 26283601, 2015). "In our previous study, we also found that PTGS2, PIK3CA, IGF1R, and IL6 commonly caused kidney cancer and inflammation, and by suppressing these genes, we can reduce the severity of kidney cancer and inflammation." (PMID 38666938, 2024). "So, all results validated the finding that isoquercitrin treatment can suppress PTGS2, PIK3CA, and IGF1R expression and thus control kidney cancer and inflammation." (PMID 38666938, 2024). "Our previous study predicted using protein-protein interaction (PPI) and molecular docking analysis that the isoquercitrin compound can control kidney cancer and inflammation by triggering potential gene targets of IGF1R, PIK3CA, IL6, and PTGS2." (PMID 38666938, 2024). "In our findings, rs3771800 CC increases the LINC01291 expression, however, showing protective signals to ccRCC, which suggests LINC01291 might regulate IGF-1R differently in kidney cancer tissue." (PMID 40622919, 2025). "Thus, we can conclude that isoquercitrin inhibits the expression of PTGS2, PIK3CA, and IGF1R gene targets, which in turn controls kidney cancer and inflammation." (PMID 38666938, 2024). "Furthermore, we performed in vitro validation of IQ efficacy using RT-PCR and qRT-PCR assays and confirmed that IQ can trigger PTGS2, PIK3CA, and IGF1R gene targets to control kidney cancer and inflammation." (PMID 38666938, 2024). "Our previous in silico protein–protein interaction (PPI) and molecular docking studies revealed that the isoquercitrin compound could trigger potential cancer-causing gene targets, such as IGF1R, PIK3CA, IL6, and PTGS2, which can regulate kidney cancer and inflammation." (PMID 38666938, 2024). "In summary, IQ can trigger the gene targets of PTGS2, IGF1R, and PIK3CA, which in turn regulate kidney cancer and inflammation." (PMID 38666938, 2024). "Next, we analysed AR activity by quantifying levels of its target genes IGF1R and MYC in enzalutamide and/or PG-treated kidney cancer cells." (PMID 32847068, 2020).
Lewis lung carcinoma (6 papers, 2010 to 2024). "In one study, cells from Lewis lung carcinoma cells (LLC) were transplanted into mice with a Igf1r KO background, meaning that the Igf1r axis was intact in cancer cells, but it was disrupted in the tumor microenvironment." (PMID 38255007, 2024).
lipodystrophy (6 papers, 2017 to 2025). A congenital or acquired disorder characterized by abnormal loss or redistribution of the adipose tissue in the body. "Severe metabolic disruption and lipodystrophy emerge when insulin receptor (IR) or insulin-like growth factor 1 receptor (IGF1R) signaling fails, highlighting their central role in adipose development." (PMID 40630101, 2025).
lung diseases (6 papers, 2013 to 2023). "Deregulation in immune responses has been associated with disturbances in IGF1 and IGF1R in typical neonatal pulmonary diseases, such as respiratory distress syndrome and bronchopulmonary dysplasia." (PMID 24391734, 2013). "IGF1R, a membrane-bound tyrosine kinase, has known implications in fibrotic lung disease pathogenesis." (PMID 38059910, 2023).
malignant astrocytomas (6 papers, 2012 to 2021). "A phase I/II clinical trial (NCT01721577), used AXL1717, an antagonist of IGF1R, as a single agent in the treatment of recurrent malignant astrocytomas." (PMID 33918704, 2021).
ovarian tumor (6 papers, 2015 to 2024). "We found that treating ovarian tumor-bearing mice with a combination of anti-PD-1/IGF1R led to a more potent response, as reflected by higher rates of up-regulated and down-regulated gene expression, compared to separate treatments." (PMID 39450263, 2024). "We previously have shown that inhibition of IGF-1R results in growth inhibition and apoptosis of ovarian tumor cells." (PMID 26510816, 2015).
renal fibrosis (6 papers, 2016 to 2025). A final common manifestation of a wide variety of chronic kidney diseases characterized by glomerulosclerosis and tubulointerstitial fibrosis. "Application of insulin-like growth factor 1 receptor (IGF-1R) inhibitor further confirmed that the regulation of autophagy and renal fibrosis by HDHW was associated with IGF-1-mediated activation of the PI3K/Akt/mTOR pathway." (PMID 36160409, 2022). "Baicalin therapy boosted insulin production and ameliorated renal fibrosis via activating the IGF-1/IGF-1R/p38 signaling pathway." (PMID 39911847, 2025). "The results of the study showed that the inhibitory effect of HDHW on autophagy and renal fibrosis was altered after blocking the binding of IGF-1 to IGF-1R, and the phosphorylation processes of PI3K, Akt, and mTOR were also blocked." (PMID 36160409, 2022). "This was accompanied by increased levels of insulin production with baicalin treatment, suggesting that baicalin may modulate the activation of the IGF-1/IGF-1R/p38 signalling pathway ameliorating STZ-induced renal fibrosis in DN rats." (PMID 39911847, 2025). "IGF-1R inhibitor is suggested to decrease mesangial matrix and exapnsion in kidneys, alleviate inflammatory response and renal fibrosis and stabilize podocyte integrity and reduce glomerular proteinuria in high-glucose-stimulated podocytes under diabetic conditions." (PMID 37034500, 2023). "Previous studies have reported that the IGF1R/p38 axis participates in renal fibrosis." (PMID 34854210, 2022). "This study first demonstrated that IGF-1R was upregulated in renal tissues collected from experimental DN, and thereafter revealed the biological effects of its inhibitor (AG-1024) on metabolic parameters, renal morphological changes, renal inflammation, and renal fibrosis." (PMID 37034500, 2023). "In conclusion, our study showed that HDHW inhibited autophagy by upregulating IGF-1 expression, promoting the binding of IGF-1 to IGF-1R, and activating the PI3K/Akt/mTOR signaling pathway, thereby reducing renal fibrosis and protecting renal function." (PMID 36160409, 2022). "The mechanism of HDHW ameliorating renal fibrosis may be that HDHW inhibits autophagy by upregulating IGF-1 expression, promoting the binding of IGF-1 to IGF-1R, and activating the autophagy-related pathway PI3K/Akt/mTOR, which in turn attenuate renal fibrosis." (PMID 36160409, 2022).
bone sarcoma (5 papers, 2014 to 2022). A sarcoma that arises from the bone. "Unfortunately, IGF1R inhibition using monoclonal antibodies (e.g. cixutumumab, dalotuzumab and robatumumab) or tyrosine kinase inhibitors (linsitinib) has not succeeded in inducing durable remissions in bone sarcomas or other tumour types so far." (PMID 33295144, 2021).
Diplopia (5 papers, 2022 to 2025). Diplopia is a condition in which a single object is perceived as two images, it is also known as double vision. "Teprotumumab is a groundbreaking drug that improves exophthalmos and diplopia by inhibiting insulin-like growth factor 1 receptor (IGF-1R)." (PMID 40094965, 2025). "Teprotumumab, an insulin-like growth factor-1 receptor approved in the US and Brazil, is recommended as first-line treatment for those with proptosis and/or diplopia." (PMID 40370423, 2025). "As a fully human monoclonal antibody targeting IGF-1R that inhibits IGF-1R-mediated signaling pathways by binding to the IGF-1R complex, teprotumumab alleviates inflammation and improves symptoms, such as proptosis and diplopia." (PMID 40587732, 2025). "Teprotumumab – an anti-IGF-1R monoclonal antibody that has recently emerged as a first-line therapy for active, moderate-to-severe TED – has demonstrated statistically significant improvements in proptosis, diplopia, clinical activity score, and quality of life compared to placebo." (PMID 38983101, 2023).
gastric adenocarcinoma (5 papers, 2014 to 2022). "Amplification, deletion or relative overexpression of INSR and IGF1R were detected in 3% and 8% of gastric adenocarcinomas, respectively." (PMID 34554347, 2022). "The INSR and IGF1R genes, which encode the insulin and type I IGF receptors, were expressed in all gastric adenocarcinomas; median relative mRNA abundances were around 10 to 12 (log2)." (PMID 34554347, 2022).
gastric tumors (5 papers, 2018 to 2025). "BMS.754807, an inhibitor targeting the insulin-like growth factor 1 receptor and insulin receptor family kinases, has been in phase I trials for the treatment of human cancers, including breast, lung, pancreatic, colon, and gastric tumor cell lines." (PMID 41007849, 2025). "Together with data from cell lines, these results clearly demonstrate that MP gastric tumors are sensitive to inhibition of IGF1R." (PMID 29725014, 2018). "This aligns with a previous study demonstrating the activation of the IGF1/IGF1R pathway in mesenchymal gastric tumors, which displayed sensitivity to Linsitinib (OSI-906), another selective IGF-1R inhibitor." (PMID 38962317, 2024).